CD4 (CD4 molecule)
Diseases named in the same sentence as CD4 in open-access papers (continued):
Sharing a sentence is not in itself a finding about the gene and the disease.
cancer (continued). "In summary, FUBP3 regulates the expression of numerous genes involved in cancer regulation, as well as genes pertinent to T cell activation, cell cycle processes, and TNF-α-induced inflammation via the NF-κB pathway in J-Lat 10.6, uninfected Jurkat, and uninfected primary CD4+T cells." (PMID 40248217, 2025). "However, a group of clinical trials related to HPV-associated cancers suggested that the CD4+/CD8+ T-cell composition did not affect outcomes, as clinical responses were observed in infusion products with different CD4+/CD8+ T-cell ratios." (PMID 40458394, 2025). "In a systematic comparison between the dynamic and non‐dynamic eQTL MR findings, we observed that 67 of 224 (30%) unique gene‐cancer pairs only showed robust MR and colocalization evidence using dynamic CD4+ T cell eQTLs, but not in any other non‐dynamic eQTL datasets." (PMID 41216857, 2025). "In addition to the predominant CD4+ and CD8+ T cells expressing αβ TCRs, a subset of primarily CD4/CD8 double-negative T cells with γδ TCRs has garnered attention as a promising immune cell population for next-generation cancer immunotherapy." (PMID 39877377, 2024). "Furthermore, high PRC1 expression had a negative correlation with CD4+ T cells, which are crucial for the immune response against cancers." (PMID 39409930, 2024). "However, in LIHC, NXPH4 exhibited a positive link to CD4+ T cells, neutrophils, macrophages, and B cells, suggesting that NXPH4 may have different immune effects in various cancers." (PMID 38613793, 2024). "A strong correlation (p < 0.05), between immunosuppressive CD4+CD25+FoxP3+ regulatory T cells and baseline sPD-L1 was observed in patients with unfavorable postoperative course of the disease, supporting the idea that these elements influence each other in cancer progression." (PMID 39055716, 2024). "Patients with immune dysregulation (dCVID) had significantly lower CD4 cell counts at diagnosis (643.57 cells/μL, SD 476.05) compared to patients without immune dysregulation (747.51 cells/μL, SD 306.49) (p=0.016), regardless of the presence of cancer." (PMID 39478863, 2024). "Moreover, analysis of The Cancer Genome Atlas (TCGA) database revealed positive correlations between PA28γ and CD44 mRNA expression, suggesting a potential role for PA28γ in facilitating CD4+ T‐cell differentiation into Th1 cells via the CCL5‐CD44 pathway." (PMID 38721005, 2024). "The enrichment of immune cells, including macrophage M0, monocytes, B cells, CD8 T cells, CD4 T cells, follicular helper T cells, and natural killer cells in ‘High SHH’ tumors, underscores a more robust and diversified immune response, potentially enhancing the body’s ability to combat cancer." (PMID 39408773, 2024). "Furthermore, CAFs from the EPIC algorithm, CD4 T cells from the TIMER algorithm, and Th1 cells from the xCell algorithm were found to correlate with the RNA expression of ENST00000326094 and ENST00000375991 in more than 20 cancer types." (PMID 39766805, 2024). "The outcomes from the CIBERSORT analysis highlighted that NXPH4 demonstrated a positive link to follicular helper T cells, M0 macrophages, and plasma cells while showing a negative correlation with CD8+ T cells, CD4+ memory T cells, and monocytes in most cancers." (PMID 38613793, 2024). "CD4 Teff could induce humeral immune response and enhance cellular immune response by secreting pro-inflammatory cytokines, and CD8 Teff could directly eliminate cancer cells by secreting granzymes, perforin and granulysin." (PMID 38348038, 2024). "Besides, the presence of CCL4 in NK cells, along with its receptor SLC7A1 in cancer cells, and CCR8 in CD4 + naïve T cells/Treg cells signified an activation of NK cells, which may predict a more favorable pathological response in pCR patients before NAT." (PMID 38566201, 2024).
cancer (continued). "Negative biomarkers such as TAMs, MDSc, CD4+ TRegs, B2M, HLA-A deletions and JAK1/2 mutations may decrease a cancer’s response to immunotherapy but are not used in clinical practice." (PMID 39722028, 2024). "In line with our hypothesis, NMUR1 was enriched in CD4+ T cells, CD8+ T cells, and macrophage cells across different cancers and positively connected with StromalScores, ImmuneScores, and ESTIMATE scores in pan-cancer." (PMID 39055918, 2024). "Interestingly, using antibody depletion experiments, we found that only CD4+T cell deletion but not CD8+T cells deletion aborted T lymphocyte cytotoxicity against HCC after Bcl6 knockout in cancer cells." (PMID 38956432, 2024). "We used laboratory test records related to HIV diagnostics and care, such as CD4 cell counts and percentages, rapid tests, qualitative Polymerase Chain Reaction (PCR), antibody and antigen tests for HIV data that was documented as HIV positive and laboratory diagnosed cancer records from SA." (PMID 38870151, 2024). "They engineered a multi-epitope cancer vaccine (P/Tr/Td) via co-aggregation of Coil29 (QARILEADAEILRAYARILEAHAEILRAD) together with the B-cell epitope PEPvIII (LEEKKGNYVVTDH), the CD8+ T-cell antigen Trp2 (SVYDFFVWL), and tetanus toxoid CD4+ T-cell epitope Td (FNNFTVSFWLRVPKVSASHLE)." (PMID 39409876, 2024). "Furthermore, similar to the cancer cachexia-model mice, the percentages of CD8+ T cells, CD4+ T cells and NK cells were significantly decreased in the spleen of LPS-injected mice (Unpaired t-test, *p < 0.05, **p < 0.01, *** p < 0.001 vs. saline-injected group)." (PMID 38685046, 2024). "While TSCM cells make up a small percentage of T cells derived from cancer patients, genetically modifying these cells using qPB followed by CAR-T cell expansion with qBT resulted in enrichment of TSCM populations as high as >80% in both the CD4+ and CD8+ CAR+ T cell populations." (PMID 39190688, 2024). "Recent immunophenotyping findings in patients with cancer have revealed that well-functioning CD8 + T cell response might be critical in surviving acute SARS-CoV-2 infection whereas B cells and CD4 + T cells are needed in achieving the ultimate viral clearance and clinical recovery." (PMID 38358552, 2024). "This adjuvant-like effect of CD4 Trm may be highly beneficial in noninfectious settings — for example, in adoptive immunotherapy against cancers." (PMID 39688906, 2024). "Extended incubation periods of 72 h demonstrated that CD-4 might not be suitable for UM-UC-5 cancer cells due to its effects on cell viability and morphology." (PMID 39409951, 2024). "Additionally, we observed a significant enrichment of CD8+ TSTR cells in cancer tissues compared to normal tissues, unlike CD4+ TSTR cells, which showed no significant enrichment." (PMID 38848147, 2024). "Previous studies have advanced the notion that CD4+ and CD8+ T cells infiltrated into malignant tumors not only signifies the ongoing host−driven anti−tumor response, but also bears a direct association with the prognosis of patients with cancer." (PMID 38297270, 2024). "Understanding the molecular mechanisms that underlie this link could, therefore, reveal pathways that can be manipulated to enhance both the CD4 and CD8 T cell responses in the context of infectious disease and cancer or limit such responses in autoimmune pathologies." (PMID 37490492, 2023). "However, it is crucial to take into account the pathological subtype of cancer and adopt a targeted approach towards suppressive CD4+Treg, rather than indiscriminately depleting all Treg or other effector T cells." (PMID 38250084, 2023). "The results showed the correlations between CDKN2A expression and different infiltration levels of CD4+ T cells, CAF, progenitors, NK T cells, Tregs, B cells, Endo, Eos, HSC, Tfh, γ/δT, neutrophils, monocytes, macrophages, dendritic cells, NK cells, Mast cells and CD8+ T cells in pan-cancer." (PMID 36961395, 2023).
cancer (continued). "Low CD4+ combined with low CD8+ may suggest a lesser but effective and balanced anti-cancer immune activation that could lead to a better OS; in contrast, high CD4+ combined with low CD8+ TIL levels may be related to a suppressed cellular immune response and consequently to worse outcomes." (PMID 36833428, 2023). "The findings showed that total T cell% and CD8+ T cell% in Omicron-infected cancer patients were lower than those in non-Omicron-infected cancer patients (both P <0.01), while CD4+T/CD8+T, total B cell count, and total B cell% were higher (P <0.05, P <0.01, and P <0.001)." (PMID 37035158, 2023). "We next investigated whether a humanized and HLA-matched model with good engraftment of functional CD4+ and CD8+ T cells could be used to characterize the immunogenicity and test the therapeutic efficacy of novel cancer vaccine platforms targeting human tumors." (PMID 37626903, 2023). "Exhausted CD8+T cells are often found in cancers, which are a type of T cell lacking effector functions, and the unconventional CD4+T cells are a type of T cell subtype similar to regulatory T cells, which are related to the immunosuppressive and tissue repair systems." (PMID 36459212, 2023). "In this study, we evaluated whether immune cells (CD4+ and CD8+ T cells) and immunosuppressive markers (PD-L1, CTLA-4, and IL-10) were present in peripheral blood and cancer tissues from GC patients, then investigated whether those findings were correlated with each other." (PMID 37153541, 2023). "Cytotoxic CD4+ and CD8+ T cells could also have decreased the cancer cells’ viability." (PMID 36674504, 2023). "These CD4+ cytotoxic T cells (CTLs) display both lytic granule (via granzyme B (GzmB) and perforin) as well as Fas/FasL mediated cytotoxicity in an MHC class II-dependent manner, and develop especially in the context of prolonged antigen stimulation, such as chronic viral infection and cancer." (PMID 37122720, 2023). "After a careful literature search, we found no studies on the prognostic aspects of CD4 in cancer." (PMID 36627705, 2023). "In addition, cytokines such as interleukins 12 and 18, interferon-γ, and CD4+ and CD8+ T-lymphocytes of the immune system may also be evoked against cancer cells." (PMID 37764996, 2023). "Of interest was the negative correlation between GPER1 and act CD4 in most cancers." (PMID 37921845, 2023). "The negative connection between CLCN4 and T cell CD4+ Th1 in most cancers shows that CLCN4 may have a potential immunological mechanism." (PMID 37671947, 2023). "While there were little changes in CD4+ and CD8+ T cell subpopulations, the DN T cells were increased in the blood by the combined treatments but significantly reduced in the PSF and the OFB which appears in the latter tissues to be little affected by the cancer cells." (PMID 38264656, 2023). "However, we found that resting memory CD4 T cells and M2 macrophages were positively correlated with the TS score, while CD8 T cells and naive CD4 T cells were negatively correlated with the TS score in many cancer types." (PMID 36721217, 2023). "Interestingly, CEP55 expression was positively correlated with six immune cell types (not only dendritic cells, but also B cells, CD4 + T cells, CD8 + T cells, neutrophils, and macrophages) in specific cancers, namely — THYM, THCA, and LIHC (except for neutrophils in THYM)." (PMID 37173675, 2023). "Moreover, thorough characterization of immune cell types using a multi-color panel rather than a single to triple stain allows to determine precise CD4+ T /CD8+ T ratio or neutrophil/T cell ratio, which have been described to be important prognostic marker in human and canine cancers." (PMID 36996049, 2023). "CD4+ T cells remained unchanged, while CD8+ T cells reduced significantly in stress group at 1 week compared with that of the control group, but remained comparable between the two groups at 2 weeks with a decreased trend along with the progression of the cancer." (PMID 37773152, 2023).
cancer (continued). "However, we found that the ratios of immunostimulatory/immunoinhibitory signatures (CD8+/CD4+ regulatory T cells, pro-/anti-inflammatory cytokines, and M1/M2 macrophages) were significantly higher in high-TMB than in low-TMB cancers (two-tailed Student’s t test, FDR < 0.1) in diverse cancer types." (PMID 36911742, 2023). "However, there is a significant positive correlation between CCNA2 and Th2 cells and significant negative correlations between CCNA2 and CD4+ central memory and effector memory T cells by the xCell estimation algorithm in almost all cancer types." (PMID 35480884, 2022). "A recent consensus by the European Organization for Research and Treatment of Cancer (EORTC) has suggested defining blood involvement based on phenotypical, rather than morphological, criteria in the presence of more than 1000/mm3 CD4+ CD26− or CD4+ CD7− cells." (PMID 35159143, 2022). "Given that CD4 + T cells, CD8 + T cells and immune suppression by CD4 + FOXP3 + regulatory T (Treg) cells represent two major factors impacting response to cancer immunotherapy, this finding suggests that the dysregulated autophagy pathways may affect the response of immunotherapy." (PMID 35550147, 2022). "Cancer cells may express MHCI molecules, display p‐MHCI complexes, and activate antigen‐experienced CD8+ T cells, but are generally not naturally equipped to present MHCII‐restricted antigens that would directly prime CD4+ T cells." (PMID 35959554, 2022). "In addition, the ratio of CD4+ memory T cells activation/resting and macrophages M1/M2 polarization was significantly higher in the high TR-DDR score group than in the low TR-DDR group in 5 kinds of cancers." (PMID 36081518, 2022). "An increased expression of TIM-3 was detected in CD4+ and CD8+ TILs in lung cancer, stomach cancer, head and neck carcinomas, and melanoma in antigen-specific T-cells of peripheral blood of patients with various types of cancer and in tumor-infiltrating DCs compared to DCs in normal tissues." (PMID 36140182, 2022). "Collectively, our study characterized the functional and transcriptomic profiles of MHC class I-restricted cytotoxic CD4+ TCR-Ts, and revealed the multifaceted killing mechanisms of this T cell subset, suggesting that they could serve as potent cancer immunotherapies." (PMID 35928827, 2022). "As confirmed by different tests, the risk score was positively associated with M0 macrophage, M1 macrophage, neutrophil, and cancer-associated fibroblast (CAF), while the correlations of NK cell, CD8 T-cell, CD4 T-cell, and B cell with risk score were negative." (PMID 36003146, 2022). "The studied population was composed of 369 men (83.1%) and 75 women (16.9%), with a median age at the first cancer event of 46 years and a median age at the SPC event of 51 years; 47.8% were MSM, 16.0% were coinfected with HCV, 9.1% were coinfected with HBV and 76.9% had a nadir CD4 count <200/mm3." (PMID 35053563, 2022). "Interestingly, CS1 enriched for B cell, CD8 T cells but may lack CD4 memory activated cells (Sup_S2); previous study showed the ratio of CD4/CD8 may play prognostic role in several cancer subtypes." (PMID 36159794, 2022). "The close relationship between IDO2 and CD4 + T cell infiltration in the MTC microenvironment, together with its potential prognostic implications, makes it possible for IDO2 to serve as an alternative drug target in cancer immunotherapy and as a new prognostic tool." (PMID 36319978, 2022). "Tregs, a type of CD4+ T-cell in charge of inhibiting the activation and differentiation of CD4+ helper T-cells and CD8+ cytotoxic T-cells, have been identified as a suppressor of antitumor immune responses and play a role as a primary mediator in cancer progression." (PMID 35326519, 2022). "As a CD4+ T cell subset, Tfhs are essential for promoting humoral immune responses mediated by B cells, and can produce a negative or positive prognostic effect on multiple cancer types." (PMID 36147509, 2022).
cancer (continued). "Although the T cell lymphoid clusters induced by SVF SPHs and mDCs were not equipped with conventional lymphoid structures and failed to recruit B cells, they contributed to the anti‐cancer response by enhancing antigen‐specific adaptive immunity, especially CD4+ T cell immunity." (PMID 36058002, 2022). "The presence of follicular dendritic cells (FDCs) and germinal centres within TLSs along with CD4+ and CD8+ and high endothelial venules (HEVs) surrounding them makes them resemble secondary lymphoid organs, which is where efficient adaptive immune response against cancer occurs." (PMID 35804943, 2022). "Moreover, in contrast to the upregulated gene sets, GSVA analysis of this gene set also demonstrated a positive correlation with immune cell infiltration and the abundancy of various anti-cancer immune cells (CD8_naive, Tr1, Th2, Th17, Tfh, NKT, MAIT, B cell, NK, γ-δ, CD4_T and CD8_T cells)." (PMID 36101357, 2022). "Previous studies in other cancer types have demonstrated that cytotoxic gene signatures can be used as ICB biomarkers, but the predictive ability of these signatures and their association with the CD4+ compartment have not been thoroughly explored in NSCLC." (PMID 35831288, 2022). "In the two female patients with malignancies, the absolute counts of CD4+ T helper cells were statistically significantly lower than in the CVID without malignancy group (p = 0.044), and the numbers of T CD4+ naive cells and RTE were in the malignancy group lower but not statistically significantly." (PMID 35402361, 2022). "Both CD4+ T cells, as well as the CD8+ T cells, are the main cells that participants in the immune response and are active in the antitumor response, which could explain the improved prognosis for in cancer patients." (PMID 35567376, 2022). "However, in the context of cancer vaccination, these precursor populations are relatively rare, so developing agonists of CD40 that can serve as adjuvants for vaccines is a promising pathway to promote both CD4+ and CD8 T cell responses following vaccination." (PMID 34282297, 2022). "Furthermore, we observed that the fluorescence signal of the probe H5 was exclusively found in a subset of cancer cells but not in other cells found in tumors (e.g., monocytes, fibroblasts, CD4 + T cells)." (PMID 35501326, 2022). "Lymphocyte count and percentages, T cell subset counts and percentages, including CD3+CD8+ counts, CD3+CD4+ counts and percentages, CD3+ counts and percentages, and the ratios of CD3+CD4+ to CD3+CD8+ were also negatively correlated, but CD3+CD8+ percentage was negatively correlated with Cancer." (PMID 35865540, 2022). "Although exhaustion of CD8+ T cells induced by cancer has been well-characterized and identified as a therapeutic target, whether CD4+ T-cell exhaustion occurs and its role in cancer has not been extensively investigated." (PMID 35784297, 2022). "Anti-cancer efficacy was evaluated using vaccines with or without CD4 epitopes." (PMID 35110563, 2022). "Notably, blockade of PD-1 in cancer treatment results in beneficial therapeutic outcomes dependent on IFN-γ producing T cells, and dependence on T-bet to secrete IFN-γ is distinct for CD4+ and CD8+ T cells." (PMID 35666747, 2022). "A recent consensus by the European Organization for Research and Treatment of Cancer (EORTC) suggested to define blood involvement (B2 according to the TNMB classification) on the basis of phenotypical criteria in the presence of more than 1,000/mm3 CD4+CD26- or CD4+CD7- cells." (PMID 35251370, 2022). "Among them, the Mast cells resting, Macrophages M2, Dendritic cells resting, T cells CD4 memory resting, T cells CD8, Plasma cells, and B cells naïve drew our attention, which were negatively correlated with the enrichment levels of m7G-related genes in most cancer types." (PMID 36226166, 2022).